RAB21 (RAB21, member RAS oncogene family)
Diseases named in the same sentence as RAB21 in open-access papers:
RAB21 is named in the same sentence as 27 diseases in open-access papers, as found by Europe PMC text mining. Sharing a sentence is not in itself a finding about the gene and the disease. The quoted sentences say what the papers report.
breast carcinoma (10 papers, 2007 to 2025). "Rab21 is associated with the control of integrin trafficking, thus modulating adhesion and motility in breast cancer cells." (PMID 24447584, 2014). "A growing number of Rab proteins such as rab5, rab11, rab21, rab25, and rab27B have been shown to be associated with tumor growth/behavior and prognosis of breast cancer patients." (PMID 22920728, 2012). "Knockdown of Rab21 inhibits integrin-mediated breast cancer cell adhesion and motility, and conversely, overexpression of Rab21 promotes cell migration and adhesion." (PMID 38695990, 2024). "The miR-183/-96/-182 cluster then promotes the migration and survival of breast cancer cells by inhibiting the expression of the tumor suppressor RAB21." (PMID 34917120, 2021). "RAB21 is known to regulate adhesion molecules and endosomal traffic of β-integrins and promote the proliferation of glioblastoma and breast cancer cells." (PMID 32759795, 2020). "All these data indicated that miR-183 targeted the RAB21 gene directly in breast cancer and induced aneuploidy." (PMID 25394902, 2014). "We identified two regulators (ZEB1 and HSF2) and one target gene (RAB21) for the miR-183/-96/-182 cluster in breast cancer cell lines." (PMID 25394902, 2014). "MiR-183 targeted RAB21 directly in breast cancer and accumulated nucleus number aberration cells." (PMID 25394902, 2014). "Also, miR-183 targets the RAB21 gene directly in breast cancer." (PMID 25394902, 2014). "HSF2 level was high in basal breast cancers, which are miR-183-enriched breast cancers; and RAB21 level was low in HER2 and basal breast cancers, which are miR-96- and/or miR-183-enriched breast cancers." (PMID 25394902, 2014). "Transfection of siRNAs for RAB21, RAB23, RAB18 and RAB3B also inhibits breast cancer cell proliferation and invasion." (PMID 24447584, 2014). "Over-expression of miR-200b or knock-down of RAB21, RAB23, RAB18 and RAB3B inhibited breast cancer cell proliferation and invasion in vitro." (PMID 24447584, 2014). "MiR-96 and miR-183 weree lower in ER+ and PR+ breast cancers than ER- and PR- breast cancers; in the meantime, their regulator, HSF2 level was lower and their target, RAB21 level, was higher in ER+ and PR+ breast cancers than ER- and PR- breast cancers." (PMID 25394902, 2014). "In our study, we identified RAB21, RAB23, RAB18 and RAB3B as novel direct targets of miR-200b in breast cancers." (PMID 24447584, 2014). "The regulations of RAB21, RAB23, RAB18 and RAB3B by miR-200b were further confirmed in breast cancer cell lines." (PMID 24447584, 2014). "The expressions of RAB21, RAB23, RAB18 and RAB3B were suppressed by transfection of miR-200b in breast cancer cells." (PMID 24447584, 2014). "In breast cancer cells, HSF2 has been identified to mediate transcription of the miR-183/-96/-182 cluster, which is highly expressed to promote tumorigenesis by directly regulating RAB21 expression." (PMID 35087869, 2021). "Members of RAB family, RAB21, RAB23, RAB18 and RAB3B were novel targets regulated by miR-200b in breast cancer, which could be of promising therapeutic significance." (PMID 24447584, 2014).
glioma (8 papers, 2017 to 2025). A benign or malignant brain and spinal cord tumor that arises from glial cells (astrocytes, oligodendrocytes, ependymal cells). "Previous studies have shown that some Rab proteins such as Rab1a, Rab21, and Rab26 are closely associated with the development and progression of many tumors, including glioma." (PMID 36922509, 2023). "Circ0030018 was upregulated and its inhibition suppressed glioma proliferation and metastasis in glioma by the miR‐1297/RAB21 axis." (PMID 37250146, 2023). "It is also reported that RAB21 acts as an oncogene in glioma cells that downregulation or silencing RAB21 can suppress the cell growth and induce cell apoptosis in glioma cell lines." (PMID 35163051, 2022). "For example, RAB21 is enhanced in glioma tissues and cells, which knockdown inhibits the proliferation and induces apoptosis of glioma cells." (PMID 35220907, 2022). "The silencing of RAB21 has also been utilized to induce apoptosis in glioma cells and can also be used to significantly inhibit cell growth." (PMID 33251139, 2020). "We found that downregulation of Rab21 by specific siRNA inserted in two glioma cell lines (T98G and U87) significantly inhibited cell proliferation and remarkably induced cell apoptosis." (PMID 29270202, 2017). "The study involved downregulation of Rab21 in two glioma cell lines (T98G and U87) through transfection with specific-siRNA." (PMID 29270202, 2017). "Our results strongly indicate that knockdown of Rab21 in glioma cell lines T98G and U87 results in a decrease in cell proliferation via cell cycle arrest and subsequent induction of apoptosis." (PMID 29270202, 2017). "Rab21 expressionsin terms of mRNA and protein levels were evaluated in five human glioma cell lines: U251, T98G, U373, SHG44 and U87." (PMID 29270202, 2017). "In this study, we characterized the roles of Rab21 (Rab GTPase 21), a member of Rab GTPase family, in glioma cells." (PMID 29270202, 2017). "PI staining was used to detect the cell cycle phase distributions in glioma cells 48 h after Rab21 siRNA transfection." (PMID 29270202, 2017). "Our findings show that silencing Rab21 exerts anti-tumor effects by altering apoptosis-related protein expressions in glioma cells." (PMID 29270202, 2017). "In addition, the silencing of RAB21 in glioma cell lines has been shown to induce apoptosis and inhibit cell proliferation." (PMID 40740986, 2025). "We inferred that Rab21 silencing can induce apoptosis and inhibit proliferation in human glioma cells, indicating that Rab21 might act as an oncogene and serve as a novel target for glioma therapy." (PMID 29270202, 2017). "We found that a significant increase occurred in Rab21 expression in T98G and U87 glioma cell lines and that downregulation of Rab21 using specific-siRNA transfected with two glioma cell lines (T98G and U87) significantly inhibits cell growth and remarkably induces cell apoptosis." (PMID 29270202, 2017). "In this study, we suggested a tumorigenic effect of Rab21 in the development of glioma." (PMID 29270202, 2017). "It was demonstrated that Rab21 might work as an oncogene and serve as a novel target for glioma therapy." (PMID 29270202, 2017). "In this study, we characterize the roles of a novel member of Rab subfamily, Rab21 in glioma." (PMID 29270202, 2017). "In this study, Rab21 was shown to have a higher expression in glioma cell linesT98G and U87." (PMID 29270202, 2017). "Consequently, we suggested that Rab21 might serve as a biomarker for prognosis and a potential target for glioma therapy." (PMID 29270202, 2017).
colorectal cancer (2 papers, 2019 to 2021). A primary or metastatic malignant neoplasm that affects the colon or rectum. "By association analysis, we were able to identify that the methylation levels of the CEP250, RAB21, and TNPO3 genes independently play crucial roles in colorectal cancer prognosis." (PMID 33670198, 2021).
leukaemia (2 papers, 2010 to 2011). "Rabgef1 has never been reported in relation to erythroid lineage or leukaemia and the encoded protein is known to interact with Rab5, Rab21 or Rab22." (PMID 20102610, 2010). "Remaining candidates (N = 62) comprised BDNF-related genes (SST), MAPK-pathway genes (KRAS, IGF1R, GNG11 and RAP1A), genes related with leukemia (SFRP1) and Rho-Proteins (DHCR7 and RAB21)." (PMID 21569303, 2011).
ovarian carcinoma (2 papers, 2022 to 2024). A malignant neoplasm originating from the surface ovarian epithelium. "Rab21 was downregulated in ovarian cancer, which led to cytokinesis failure and induced aneuploidy, further underwent malignant transformation and tumorigenicity." (PMID 36203437, 2022).
acute pancreatitis (1 paper, 2020). An acute inflammatory process that leads to necrosis of the pancreatic parenchyma. "Further, RAB21 mediates acute pancreatitis through interaction with the TRAF3-MKK3 complex." (PMID 32759795, 2020).
amyloidosis (1 paper, 2021). A disorder characterized by the localized or diffuse accumulation of amyloid protein in various anatomic sites. "Specifically, the proteins involved in amyloidosis, including optineurin (OPTN), ras‐related protein Rab‐21 (Rab21), dynamin 1 (DNM1), peroxisomal bifunctional enzyme (EHHADH), fermitin family homolog 2 (FERMT2), E3 ubiquitin‐protein ligase UBR1 were increased in T2DM‐MCI compared with T2DM‐nMCI." (PMID 34528736, 2021).
follicular thyroid carcinoma (1 paper, 2025). "Therefore, we examined whether the knockdown (KD) of RAB21 expression in FTC-133 cells, a follicular thyroid carcinoma cell line, might affect malignant phenotypes such as invasion and migration." (PMID 40740986, 2025).
head and neck squamous cell carcinoma (1 paper, 2025). A squamous cell carcinoma that arises from any of the following anatomic sites: lip and oral cavity, nasal cavity, paranasal sinuses, pharynx, larynx, and salivary glands. "Moreover, a recent study reported that EVs derived from head and neck squamous cell carcinoma carrying RAB21 homed to lung macrophages and were incorporated into them through an interaction with integrin-β1 on the macrophage surface, eventually inducing the immunosuppression of these cells." (PMID 40740986, 2025).
liver cancer (1 paper, 2017). An epithelial or non-epithelial malignant neoplasm that arises from the liver. "The expression of Rab21 was reported to regulate the adhesion and migration of several tumor cell types, including breast, prostate and liver cancer." (PMID 29270202, 2017).
lung carcinoma (1 paper, 2025). "In addition, the FFPG-Lip-PTX complex was better and more quickly internalized in lung cancer cells, due to the specific affinity between FFPG and Rab21, which promoted the accumulation of FFPG-Lip-PTX into lung cancer tissues." (PMID 39861741, 2025).
peritoneal effusions (1 paper, 2005). "Pleural effusions had significantly higher expression of the angiogenic inducer CYR61, RAB21, glutathione S-transferase A4 (GSTA4), and several chemokines when compared to peritoneal effusions." (PMID 16042759, 2005).
prostate carcinoma (1 paper, 2022). A carcinoma that arises from epithelial cells of the prostate gland. "Inversely, RAB21 is downregulated in prostate cancer and suppresses tumor progression." (PMID 35220907, 2022).
squamous carcinoma (1 paper, 2024). "RAB21 helps tumor-associated fibroblasts to invade squamous carcinoma cells." (PMID 39309198, 2024).
cancer (13 papers, 2010 to 2025). A tumor composed of atypical neoplastic, often pleomorphic cells that invade other tissues. "For example, chromosomal deletion and loss of Rab21, a regulator of endocytic trafficking of integrins, has been found in cancer that leads to the accumulation of multinucleate cells in cancer." (PMID 22121362, 2012). "In addition to Rab11 and Rab25, Rab21 is required for carcinoma-associated fibroblasts to promote invasion by cancer cells and facilitates integrin α5β1 accumulation for force-mediated matrix remodeling at the plasma membrane." (PMID 22121362, 2012). "Their findings suggested that RAB21 is essential for cancer cell survival and proliferation, particularly in the glucose-deprived tumor microenvironment." (PMID 40740986, 2025). "In several cancer entities, both, active and inactive β1 receptors are internalized via clathrin- and dynamin-dependent routes to Rab4a-, Rab5-, or Rab21-positive early endosomes." (PMID 33916607, 2021). "One drawback of our study is that it solely used SW480 cells to define the role of ATG5 and RAB21 in cancer cell hyperproliferation." (PMID 31383875, 2019). "This class of compounds exert their effects partly through disrupting the function of Rab proteins, and we show a new role for Rab21 in promoting cancer cell invasion promoted by CAFs." (PMID 19953096, 2010). "Rab21 is required for CAFs to promote invasion by cancer cells and facilitates integrin α5 accumulation for force-mediated matrix remodeling at the plasma membrane." (PMID 21143914, 2010). "Moreover, our findings on the functional role of RAB21 in cancer cell migration provide insights into the molecular mechanisms underlying the malignant progression of FTC, potentially opening new avenues for therapeutic interventions." (PMID 40740986, 2025). "Rab21 also enhances cancer cell adhesion and migration by regulating integrin endocytosis." (PMID 22121362, 2012). "Rab21 is involved in promoting cancer cell invasion promoted by CAFs." (PMID 21143914, 2010). "Rab21 is required for CAFs to promote the invasion of cancer cells." (PMID 19953096, 2010). "Interestingly, the role of RAB21 is contradictory in cancer." (PMID 35220907, 2022). "Several proteins related to cancer development and progression were identified in the list of abundant proteins in FTC, including Ras-related protein Rab-21 (RAB21), Keratin 13 (KRT13), and Serum amyloid A1 (SAA1)." (PMID 40740986, 2025). "In addition, RAB21 could modulate multidrug resistance in cancer cells." (PMID 35220907, 2022). "FN is a major host ECM component that induces actin remodeling in the parasite in a RAB21-dependent manner, forming invadosomes that promote the chemotactic migration of the metastatic cancer cells and non-transformed cells by remodeling the ECM." (PMID 39228892, 2024).
tumor (11 papers, 2007 to 2025). "Rab21 is a member of the Rab subfamily, which has been identified as required for tumor-associated fibroblasts to promote the invasion of squamous carcinoma cells." (PMID 29270202, 2017). "As loss of RAB21 in the tumor would induce chromosome number aberrations, we checked the nucleus aberration in miR-183/-96/-182 cluster overexpression MCF-7 cells." (PMID 25394902, 2014). "More extensively characterized Rab proteins such as rab25 and rab21 were shown to be associated with increase in tumor cell proliferation and are required to promote cancer cell invasion." (PMID 22920728, 2012). "Loss of RAB21 in the tumor induces chromosome number aberrations and malignancy." (PMID 25394902, 2014). "Rab21 cooperated with the retromer complex for the retrograde trafficking of cargo and promoted tumour proliferation." (PMID 40293576, 2025). "Organoid lines also exhibited somatic mutations in RCC‐related genes which were in concordant with respective tumor including ESPL1, SMARCB1, RAB21, NCOR1, NLRC5, NOTCH2, and FOXA2 mutations." (PMID 38923304, 2024). "HCT116 and Caco-2/15 cells, both of which exhibited high autophagic flux under glucose starvation in vitro, were sensitive to autophagy inhibition and showed a 50% decreased tumor growth upon ATG5 or RAB21 depletion." (PMID 31383875, 2019). "Contrary to results obtained in vitro, depletion of either ATG5 or RAB21 markedly affected tumor growth." (PMID 31383875, 2019). "Collectively, these results indicate that ATG5 or RAB21 depletion in CRC cells can either inhibit or promote tumor growth." (PMID 31383875, 2019). "Rapamycin treatment also reduced tumor growth, although less effectively and was moreover ineffective in RAB21-depleted cells." (PMID 31383875, 2019). "In summary, miR-200b low ISH staining was seen in 90% (9/10) tumor samples, while positive rates for RAB21, RAB23, RAB18 and RAB3B IHC staining were 80%, 80%, 90%, 100% respectively." (PMID 24447584, 2014). "Compared with normal breast tissue, miR-200b expression was down-regulated in tumor tissue, while the contrary situations were found for RAB21, RAB23, RAB18 and RAB3B IHC staining." (PMID 24447584, 2014). "Rab21 KO MDA-MB-231 cells formed smaller tumours than controls in vivo." (PMID 40293576, 2025). "Overall, Rab21 promoted endosomal recycling, cellular energetics, and tumour progression." (PMID 40293576, 2025). "Interestingly, some members of the RAB family such as RAB21 and RAB25 are closely linked with tumor cell invasion and migration." (PMID 35220907, 2022). "There were no major macroscopic differences between control and ATG5- or RAB21-depleted tumors for all cell types, suggesting that the varying tumor sizes could be due to the modulation of apoptosis or proliferation." (PMID 31383875, 2019). "Hence, the observed growth phenotypes most probably result from early effects of ATG5 and RAB21 depletion on tumor growth and would presumably be stronger in the context of a prolonged knockdown (or knockout)." (PMID 31383875, 2019). "Finally, Rab21 cooperated with the retromer complex for the retrograde trafficking of SLC2A1 and IGF2R and promoted tumour proliferation." (PMID 40293576, 2025). "No significant changes were observed in PARP or Caspase 3 cleavage between control and ATG5- or RAB21- depleted cells, indicating that apoptosis induction was not responsible for the decreased tumor size in HCT116 cells." (PMID 31383875, 2019). "Surprisingly, knockdown of ATG5 and RAB21 in SW480 and LoVo resulted in increased tumor growth, whereas SW620 and HT29 cell lines were non-responsive to autophagy inhibition and grew to similar extents whether in control or treated conditions." (PMID 31383875, 2019). "Of note, although knockdown efficiencies were variable between cell lines and did not persist over the full time course of tumor growth, increased p62 staining was observed in ATG5- and RAB21-depleted CRC tumors, suggesting that autophagy was impaired, in our CAM model." (PMID 31383875, 2019).
adenocarcinoma (1 paper, 2025). A common cancer characterized by the presence of malignant glandular cells. "Knockdown of Rab21 impairs integrin-mediated cell adhesion and motility in human adenocarcinoma cells." (PMID 40627460, 2025).
infection (1 paper, 2020). The state of being infected such as from the introduction of a foreign agent such as serum, vaccine, antigenic substance or organism. "We found that endocytic Rabs are selectively recruited to the vacuole of T. cruzi, among them Rab22a, Rab5, and Rab21 right away after the infection followed by Rab7 and Rab39a at later times." (PMID 33194787, 2020).
RAB21 also shares sentences with these, for which no sentence is quoted: Alzheimer disease (2 papers); glioblastoma (2); breast invasive carcinoma (1); depression (1); hepatocellular carcinoma (1); pancreatic ductal adenocarcinoma (1); Parkinson disease (1); Pleural effusion (1); stomach adenocarcinoma (1).